AGTRAP (angiotensin II receptor associated protein)
Diseases named in the same sentence as AGTRAP in open-access papers:
AGTRAP is named in the same sentence as 69 diseases in open-access papers, as found by Europe PMC text mining. Sharing a sentence is not in itself a finding about the gene and the disease. The quoted sentences say what the papers report.
Hypertension (10 papers, 2017 to 2024). The presence of chronic increased pressure in the systemic arterial system. "ENPEP converts angiotensin II to Angiotensin III, which activates the angiotensin II receptor together with AGTRAP, thereby promoting vasodilation and protecting against hypertension." (PMID 31699050, 2019). "A recent study on illnesses like hypertension and nephrotic syndrome has focused on AGTRAP." (PMID 34840632, 2021).
glioma (5 papers, 2021 to 2026). A benign or malignant brain and spinal cord tumor that arises from glial cells (astrocytes, oligodendrocytes, ependymal cells). "Angiotensin II receptor-associated protein (AGTRAP) is upregulated in glioma, but its functional role and downstream programs remain insufficiently defined." (PMID 41689202, 2026). "Since M2 macrophages can drive tumour progression through immunosuppression in gliomas, it would be interesting for future studies to elucidate the exact involvement of AGTRAP in this context." (PMID 38672281, 2024). "According to our results, we found that our study is consistent with the past studies which researched AGTRAP in glioma and hepatocellular carcinoma." (PMID 36060798, 2022). "Furthermore, our study revealed that high expression of AGTRAP is significantly related with poor prognosis in glioma, liver cancer, kidney chromophobe, and so on." (PMID 36060798, 2022). "In addition to metabolic functions, several bioinformatic analyses demonstrated that AGTRAP can be used as a component of prognostic signatures in brain lower grade glioma, tongue squamous cell carcinomas, and melanoma, revealing the potential of prognostic ability of AGTRAP." (PMID 36060798, 2022).
hepatocellular carcinoma (5 papers, 2021 to 2024). A malignant tumor that arises from hepatocytes. "The angiotensin II receptor-associated protein (AGTRAP) has been confirmed to be related with metabolic products in metabolic diseases and can drive the progression of hepatocellular carcinoma and colon carcinoma." (PMID 36060798, 2022). "While no detailed biomarker studies in IDH wild-type GBM were available for comparison, studies in other types of solid cancer, such as hepatocellular carcinoma, cervix carcinoma and tongue squamous cell carcinoma, showed that AGTRAP associated with the poor outcome of those patients." (PMID 38672281, 2024). "The metabolic gene rapid visualizer, Cancer Cell Line Encyclopedia, Human Protein Atlas, and Hepatocellular Carcinoma Database were used to analyze the expression of AGTRAP in HCC tissues and normal liver tissues or adjacent tissues." (PMID 34595113, 2021). "Finally, significant high expression of AGTRAP was found in breast cancer, colon cancer, head and neck squamous carcinoma, pancreatic adenocarcinoma, glioblastoma multiforme, and hepatocellular carcinoma." (PMID 36060798, 2022). "Based on our bioinformatics analysis, it suggested that AGTRAP could be involved in the immune microenvironment of hepatocellular carcinoma, and related to MAPK signaling pathway." (PMID 34595113, 2021). "Therefore, we speculate that AGTRAP may regulate immune microenvironment of hepatocellular carcinoma through MAPK signaling pathway." (PMID 34595113, 2021). "Nevertheless, the possible role of AGTRAP in hepatocellular carcinoma (HCC) remains unrecognized." (PMID 34595113, 2021). "In addition, the abnormal protein expression of AGTRAP has been confirmed in the CPTAC samples across breast cancer, colon cancer, head and neck cancer, pancreatic cancer, glioblastoma multiforme, and hepatocellular carcinoma." (PMID 36060798, 2022).
Insulin resistance (4 papers, 2014 to 2022). Increased resistance towards insulin, that is, diminished effectiveness of insulin in reducing blood glucose levels. "AGTRAP overexpression has also been associated with insulin resistance." (PMID 31699050, 2019).
gastric cancer (3 papers, 2018 to 2022). A primary or metastatic malignant neoplasm involving the stomach. "Subsequently, high expression of AGTRAP was identified in breast cancer, pancreatic cancer, and gastric cancer." (PMID 36060798, 2022). "The results showed that AGTRAP is significantly highly expressed in breast cancer, pancreatic cancer, and gastric cancer, which verifies our bioinformatic analysis." (PMID 36060798, 2022). "To further verify the abnormal expression of AGTRAP in pan-cancer, we conducted qRT-PCR to detect the mRNA expression in breast cancer, pancreatic cancer, and gastric cancer." (PMID 36060798, 2022). "This is also in accordance with AGTRAP-BRAF gene fusion detected in gastric cancer." (PMID 34595113, 2021).
colon carcinoma (2 papers, 2021 to 2022). "However, in our study, the high expression of AGTRAP in colon cancer showed better survival which is contrary to a previous study." (PMID 36060798, 2022).
melanoma (2 papers, 2020 to 2022). A malignant, usually aggressive tumor composed of atypical, neoplastic melanocytes. "Finally, we identified AGTRAP, a HIF1α direct target related to reduced PFS in melanoma and to tumor growth and angiogenesis in Lewis lung carcinoma." (PMID 32204550, 2020).
acute lymphoblastic leukemia (1 paper, 2022). Leukemia with an acute onset, characterized by the presence of lymphoblasts in the bone marrow and the peripheral blood. "Significantly lower AGTRAP expression in tumor samples than in normal tissues was demonstrated in LUSC (lung squamous cell carcinoma), ALL (acute lymphoblastic leukemia), LAML (acute myeloid leukemia), KICH (p < 0.0001), and PCPG (pheochromocytoma and paraganglioma) (p < 0.05)." (PMID 36060798, 2022).
alcoholism (1 paper, 2022). "Furthermore, alcoholism is another related pathway of AGTRAP in cancer progression." (PMID 36060798, 2022).
fibrosis (1 paper, 2022). the formation of excess fibrous connective tissue in an organ or tissue in a reparative or reactive process. "Under cardiac stresses, increased FAM114A1 may promote cardiac fibrosis and remodeling through the FAM114A1/AGTRAP/AT1R axis in CFs." (PMID 35671117, 2022).
mesothelioma (1 paper, 2022). A usually malignant and aggressive neoplasm of the mesothelium which is often associated with exposure to asbestos. "Contrarily, highly expressed AGTRAP showed better OS in MESO (mesothelioma) and THCA (p < 0.05), better DFS in COAD (p < 0.05), better DSS in BRCA and THCA (p < 0.05), and better PFS in BRCA (p < 0.05)." (PMID 36060798, 2022).
Stroke (1 paper, 2015). Sudden impairment of blood flow to a part of the brain due to occlusion or rupture of an artery to the brain. "Similar analyses of SHRSP-specific genes revealed that angiotensinogen (Agt), angiotensin II receptor-associated protein (Agtrap) and apolipoprotein H (Apoh) were possible candidate genes responsible for triggering strokes." (PMID 26165378, 2015).
uveal melanoma (1 paper, 2022). A melanoma derived from melanocytes of the uveal tract. "Highly expressed AGTRAP was associated to significantly poor OS in LGG, LIHC, and UVM (uveal melanoma) (p < 0.05), significantly poor DFS in LGG and STAD (p < 0.05), significantly poor DSS in KIRC, LGG, LIHC, STAD, and UVM, and significantly poor PFS in LGG, HNSC, LIHC, and STAD (p < 0.05)." (PMID 36060798, 2022).
tumor (9 papers, 2020 to 2026). "Then, immune cell infiltration analysis was conducted to further expose the association between AGTRAP expression and tumor microenvironment in pan-cancer." (PMID 36060798, 2022). "Recently, it has been reported that angiotensin II receptor-associated protein (AGTRAP) plays a substantial role in tumor progression." (PMID 34595113, 2021). "In addition, the connection between AGTRAP and tumor microenvironment, tumor mutation burden, and immune-related genes was proven." (PMID 36060798, 2022). "Furthermore, some studies supported that AGTRAP is also associated with tumor progression." (PMID 36060798, 2022). "We assessed the expression of AGTRAP protein in HCC tumor tissues (T) and paired adjacent tissues (A)." (PMID 34595113, 2021). "The protein expression of AGTRAP was higher in tumor tissues than in adjacent tissues and was mainly localized in cell plasma." (PMID 34595113, 2021). "Although current knowledge suggests that AGTRAP plays an important role in tumor occurrence and development, more research is required to elucidate its effects on tumors." (PMID 34595113, 2021). "Consistent with our expectations, we found that patients with higher tumor grades had higher AGTRAP levels, accompanied by worse survival outcomes." (PMID 34595113, 2021). "In cancer, AGTRAP can promote tumour progression through activation of the MAPK and AKT/mTOR signaling pathways, but potentially also through regulation of immunological processes, such as T-cell exhaustion or recruitment of pro-inflammatory and immunosuppressive immune cells." (PMID 38672281, 2024). "Furthermore, very recent studies found a direct correlation between AGTRAP levels and the numbers of tumour-infiltrating M2 macrophages in GBM." (PMID 38672281, 2024). "In conclusion, our study indicated that AGTRAP might regulate these metabolism-related and immune-related pathways, leading to tumor development." (PMID 36060798, 2022). "In this study, we showed that AGTRAP and its related genes show abnormal expressions in different types of cancers that might affect tumor progression through regulating immune-related and metabolism-related pathways." (PMID 36060798, 2022). "By combining previous studies and our analysis, we could speculate that AGTRAP might increase the M2 macrophage infiltration in TME which leads to tumor development." (PMID 36060798, 2022). "Moreover, in KICH (kidney chromophobe), AGTRAP expression in tumor samples is significantly lower than that in normal tissues (p < 0.001)." (PMID 36060798, 2022). "First, AGTRAP mRNA expression in tumor samples and normal tissues was analyzed across TCGA dataset." (PMID 36060798, 2022). "Thus, in addition to the mRNA expression analysis, AGTRAP data from CPTAC was analyzed by comparing the tumor samples to normal tissues." (PMID 36060798, 2022). "Notably, AGTRAP was overexpressed in tumor tissues in all pancancers with paired samples (P < 0.05)." (PMID 34840632, 2021). "We found that the AGTRAP protein level is also overexpressed in tumor samples." (PMID 34840632, 2021). "Here, we found that AGTRAP might affect the tumor microenvironment by regulating immune cells, especially neutrophils and T cells, and may serve as an immunotherapy target in HCC." (PMID 34595113, 2021). "Moreover, the heat map showed that AGTRAP expression was higher in HCC tumor tissues than in adjacent tissues (p < 0.001)." (PMID 34595113, 2021). "A growing amount of research suggests that AGTRAP may play an important role in tumor progression." (PMID 34595113, 2021). "Moreover, we demonstrated that cytoplasmic p16 interacted with CDK4 and other unreported proteins, such as BANF1, AKAP8 and AGTRAP, which could sequester p16 to avoid nuclear translocation, and then, impair its anti-tumor function." (PMID 32204550, 2020).
tumor (continued). "The results showed that the levels of AGTRAP, DIVERSIN, NEDD8c and RRM1 were significantly higher in the tumour tissues compared to the healthy brain parenchyma." (PMID 38672281, 2024). "AGTRAP, DIVERSIN, cytoplasmic NEDD8 (NEDD8c) and RRM1 were significantly overexpressed in tumour tissues compared to the healthy brain, while the opposite was observed for ALKBH3." (PMID 38672281, 2024). "High expressions of AGTRAP, SH3KBP1, and RBMX were found in tumor tissues and correlated with a poor prognosis." (PMID 36338975, 2022). "Although AGTRAP (ATRAP) is found in a variety of human tissues, little is known about it in tumor tissue." (PMID 34840632, 2021). "A positive trend was found between expression of AGTRAP in HCC and the progression of tumor grade." (PMID 34595113, 2021).
cancer (7 papers, 2009 to 2023). A tumor composed of atypical neoplastic, often pleomorphic cells that invade other tissues. "In view of the deficiency of studies of AGTRAP in cancers, relevant research studies are urgently needed." (PMID 36060798, 2022). "Survival analysis showed that 12 kinds of cancers have poorer OS significantly related with the overexpression of AGTRAP and 2 types of cancers have better OS associated with overexpressed AGTRAP." (PMID 36060798, 2022). "AGTRAP expression in different kinds of cancer is variously associated with immune checkpoint genes." (PMID 36060798, 2022). "Importantly, MHC-related genes were more associated with AGTRAP expression than the chemokine-related and receptor-related genes in pan-cancer." (PMID 36060798, 2022). "The heatmap shows that in almost all kinds of cancers, AGTRAP expression is variously related with immune and stromal cells." (PMID 36060798, 2022). "A significant difference of AGTRAP expression in different pathological stages was demonstrated across various cancer types, such as ESCA, KICH, BLCA, KIRC, LIHC, PAAD, and UCS (p < 0.05)." (PMID 36060798, 2022). "Afterward, enrichment pathways of single AGTRAP in different kinds of cancers were evaluated to further reveal the potential mechanism." (PMID 36060798, 2022). "We also explored the putative functional mechanisms of AGTRAP across pan-cancer, such as endoplasmic reticulum pathway, endocytosis pathway, and JAK-STAT signaling pathway." (PMID 36060798, 2022). "Regarding the RNA modification genes, correlation analysis was performed for these genes and AGTRAP across various cancers." (PMID 36060798, 2022). "Our results demonstrated that AGTRAP was highly expressed in these cancer types, which is consistent with the analysis across CPTAC dataset." (PMID 36060798, 2022). "In order to further reveal the mechanism of AGTRAP in influencing cancer progression, we analyzed the correlation between AGTRAP and some vital genes including immune checkpoint, RNA methylation, immunoregulator, and MMR." (PMID 36060798, 2022). "In order to evaluate the expression of AGTRAP in different pathological stages in pan-cancer, we conducted the “Pathological Stage Plot” module in GEPIA2." (PMID 36060798, 2022). "In view of the prediction ability of TMB, MSI, and neoantigen in diverse cancers, potential of AGTRAP for predicting drug responses combined with these novel biomarkers in pan-cancer is promising." (PMID 36060798, 2022). "TCGA cancer cases were divided into low- and high-expression subsets according to AGTRAP expression, and then the correlation between AGTRAP expression and prognosis was analyzed." (PMID 36060798, 2022). "From our results, we found that correlations between AGTRAP expression and diverse immune cells can be found in almost all kinds of cancers." (PMID 36060798, 2022). "In our study, the high expression of AGTRAP was found in 14 kinds of cancer and low expression in 1 cancer type from TCGA datasets." (PMID 36060798, 2022). "Further explorations are urgently needed to reveal the precise functions and mechanisms of AGTRAP in cancer patients." (PMID 36060798, 2022). "In addition, GBM, HNSC, LUSC, PRAD, THCA, and THYM are cancers in which AGTRAP expression is significantly related with all the five MMR genes." (PMID 36060798, 2022). "Correlation analyses were performed between these biomarkers and AGTRAP expression in pan-cancer." (PMID 36060798, 2022). "Therefore, coexpression analysis of MMR genes and AGTRAP in pan-cancer was conducted and presented by the heatmap." (PMID 36060798, 2022). "In order to explore the functions and mechanisms of AGTRAP in cancers which were highly unknown, we extracted data from online databases to conduct a pan-cancer analysis." (PMID 36060798, 2022). "However, details of AGTRAP about expression, survival, mechanism, and treatment response in diverse cancers are highly unclear." (PMID 36060798, 2022).
cancer (continued). "Notably, LGG, NB, BLCA, SARC, UVM, and PCPG are cancers which have more positive coexpression of AGTRAP and cell infiltration, while OV, THYM, LAML, UCEC, and STES have more negative coexpression." (PMID 36060798, 2022). "Moreover, the analysis of combination of TCGA and GTEx datasets suggested that AGTRAP was highly expressed in 26 kinds of cancer and lowly expressed in six cancer types." (PMID 36060798, 2022). "In addition, AGTRAP expression is significantly related with ImmuneScore in 19 types of cancers and with StromalScore in 17 types of cancers, which also reveals the relationship between AGTRAP and cancer immunity." (PMID 36060798, 2022). "Importantly, we found that AGTRAP expression was positively related with M2 macrophage infiltration among 25 cancer types." (PMID 36060798, 2022). "Furthermore, the expression of AGTRAP mRNA in cancer tissues was higher than that in normal tissues." (PMID 34595113, 2021). "As assessed through an array of cancer cell lines, AGTRAP was highly expressed in HCC cells." (PMID 34595113, 2021). "However, compared to other targets, there has been relatively little research on AGTRAP and cancer, particularly with regard to its specific mechanisms in HCC." (PMID 34840632, 2021). "In addition, as a pan-cancer bioinformatic study, although with reasonable logic and comprehensive analysis for diverse cancers, combining with the verification of AGTRAP expression in three cancer types, deeper mechanisms of AGTRAP in each cancer type still need to be explored in the future." (PMID 36060798, 2022). "Therefore, there might be some potential mechanisms between these molecules and AGTRAP in cancers that need to be further explored." (PMID 36060798, 2022). "However, AGTRAP levels were higher in HCC cell lines (Hep G2) than in most cancer cell lines." (PMID 34595113, 2021). "Additionally, the level of AGTRAP in HCC tissues was the lowest among the cancer samples." (PMID 34595113, 2021). "According to our study, AGTRAP shows great relationships with immune checkpoint, RNA methylation, immunoregulator, and MMR genes in pan-cancer, which means that there possibly exist some interactions between them influencing cancer progression." (PMID 36060798, 2022). "However, functions of AGTRAP in other kinds of cancers are unclear, and a pan-cancer analysis of AGTRAP has not been carried out." (PMID 36060798, 2022). "Genes and AS events enrolled in the comprehensive prognostic signature included RHOT1 (ES), SH3KBP1 (AP), AGTRAP (AA), PACS2 (AP), RBPMS (AT), B3GNTL1 (AP), MOBP (AT), NPHP3 (ES), ABCC5 (RI), FKTN (ES) and FKBP8 (AA), many of which are known to play important roles in cancer biology." (PMID 32467664, 2020).
metabolic disorders (5 papers, 2014 to 2022). "As a protein that regulates visceral obesity-related metabolism, AGTRAP has been widely researched in metabolic disorders." (PMID 36060798, 2022).
AGTRAP also shares sentences with these, for which no sentence is quoted: Obesity (4 papers); cardiac hypertrophy (3); tongue squamous cell carcinoma (3); cervix cancer (2); diabetes (2); glioblastoma (2); lung adenocarcinoma (2); renal fibrosis (2); Sepsis (2); viral infection (2); acute myeloid leukemia (1); acute myocardial infarction (1); Alzheimer disease (1); amyotrophic lateral sclerosis (1); autoimmune thyroid disease (1); bladder urothelial carcinoma (1); breast carcinoma (1); breast invasive carcinoma (1); cardiovascular diseases (1); chronic kidney disease (1); colorectal cancer (1); ductal carcinoma in situ (1); endometrial cancer (1); head and neck cancer (1); heart disease (1); IgA nephropathy (1); invasive ductal carcinoma (1); kidney cancer (1); Lewis lung carcinoma (1); liver cancer (1).
A further 23 diseases each share a sentence with AGTRAP in 1 paper.